TEX28P1 (TEX28 pseudogene 1)
Synonyms: pTEX
Gene: Unprocessed pseudogene on chromosome X (154,196,471 to 154,213,487, reverse strand). Ensembl gene ENSG00000274962.
Subcellular location: Membrane